ABCA1 (ATP binding cassette subfamily A member 1)
Diseases named in the same sentence as ABCA1 in open-access papers (continued):
Sharing a sentence is not in itself a finding about the gene and the disease.
melanoma (continued). "Here, we identified a tumor protective function against B16F10 melanoma and MB49 bladder cancer in mice with myeloid deficiency in ABCA1 (A1−M/−M) or ABCA1 and ABCG1 (DKO)." (PMID 29069761, 2017). "Herein, we explored potential roles in melanoma tumorigenesis for host scavenger receptor class B, type 1 (SR-B1), and ATP-binding cassette transporters A1 (ABCA1) and G1 (ABCG1), all mediators of apoA-I and HDL sterol and lipid transport function." (PMID 29069761, 2017). "We show here that the ability of Curcumin to induce apoptosis and to act on NFκB is restored by knocking down ABCA1 in treatment resistant M14 melanoma cells." (PMID 20030852, 2009). "Here we show that resistance of M14 melanoma cells to Curcumin is due to over-expression of the cholesterol transporter ABCA1 and demonstrate that silencing of this multi-drug resistance gene leads to better response of M14 cells to the polyphenol." (PMID 20030852, 2009). "However, ABCA1 seems to be somehow involved in the progression of melanoma, because its increased expression was demonstrated in more advanced tumors; it was also correlated with a shorter overall survival." (PMID 39175042, 2024). "Moreover, we demonstrate the impact of the ABCA1 activity on human melanoma cells, and more precisely on their motility." (PMID 37312227, 2023). "Finally, we put another brick in understanding the ABCA1 influence on melanoma cells PM organization leading to their metastatic transition and aggressiveness in the human body." (PMID 37312227, 2023). "Moreover, ABCA1 activity regulated the lateral organization of the plasma membrane in melanoma cells." (PMID 37312227, 2023). "Depletion or inhibition of ABCA1 impacts invasion capacities of aggressive melanoma cells." (PMID 37312227, 2023). "The combination of our clinical and in vitro results advocates that ABCA1 might be used as a potential clinical marker for aggressive melanoma and eventually a target in anti-cancer therapies." (PMID 37312227, 2023). "Finally, by interrogating available scRNA-seq datasets of tumor-infiltrating immune cells, we reported a significant enrichment of melanoma-infiltrating monocytes/macrophages over-expressing the LXR target genes ABCA1 and SCD1 in ICB-resistant patients." (PMID 36792589, 2023). "Additionally, in the two other melanoma cell lines highly expressing ABCA1, namely WM1341D and WM9, we also observed a significant diminution of the total migrated distance as well as a loss of invasion potential upon probucol treatment." (PMID 37312227, 2023). "In addition, downregulated ABCA1 expression was found to prevent melanoma and bladder tumor growth in a syngeneic murine melanoma tumor model with a myeloid-specific Abca1 deletion." (PMID 33562440, 2021). "We next examined whether the tumor inhibition observed in animals with myeloid ablation of ABCA1 was specific to B16F10 melanoma." (PMID 29069761, 2017). "Therefore, ABCA1 may contribute to tumor progression and poor prognosis, suggesting ABCA1 to be a potential metastatic marker in melanoma." (PMID 37312227, 2023). "Statistical evaluation of the results concerning the effects of ABCA1 on response to Curcumin revealed that knocking-down the multidrug resistance gene alone already inhibits expression of the NFκB subunit p65 and the survival factors bcl2 and survivin and induces apoptosis in melanoma cells." (PMID 20030852, 2009). "In this study we investigated the role of host cholesterol transporters ABCA1, ABCG1, and the HDL receptor SR-B1, on melanoma and bladder tumor growth." (PMID 29069761, 2017). "Upon T0901317 treatment, expressions of LXR target genes, ABCA1 and SREBF1, were induced in B16F10, indicating LXRs were functional in B16F10 melanoma cell line." (PMID 24564864, 2014).
melanoma (continued). "For eraser genes, studies have found that knocking down FTO in mouse models could increase the tumor’s sensitivity to PD-1 therapy, while ALKBH5 promoted melanoma cell proliferation, migration, and invasion by acting on FOXM1 and ABCA1." (PMID 41301778, 2025). "There are limited data regarding the importance of ABC-cassette genes in human melanoma and no direct link between ABCA1 and human melanoma development has been reported to date." (PMID 37312227, 2023). "ABCA1, ABCG1 (HDL receptor) and SRBP-1 (HDL receptor) are candidates for further investigation as potential mediators of apoA-I anti-tumor activity in B16F10 melanoma." (PMID 32477466, 2020). "Our studies newly identify a potential melanoma tumor-permissive role for SR-B1 and myeloid ABCA1 in non-tumor somatic cells in tumor bearing hosts." (PMID 29069761, 2017). "To further confirm the in vivo anti-melanoma activity of T0901317 was mediated through LXR signaling, we analyzed the expression of LXR target genes, ABCA1 and SREBF1, in tumors, and found that expressions of ABCA1 and SREBF1 were increased in T0901317-treated melanoma." (PMID 24564864, 2014). "Melanoma is therefore most likely not a good target for Curcumin treatments unless patients are selected on the base of ABCA1 expression." (PMID 20030852, 2009). "Thereby we were able to identify essentially a single ATP-binding cassette transporter gene, ABCA1 to be responsible for the lack of response to Curcumin in M14 melanoma cells." (PMID 20030852, 2009). "Among these genes, we found that ATP-binding cassette transporter A1 (ABCA1), a functional membrane protein facilitating cholesterol efflux, presented the most consistent raised m6A level after ALKBH5 knockdown, and its mRNA level increased in shALKBH5 A375 melanoma cells compared to control cells." (PMID 38481816, 2024). "However, no direct link between human melanoma progression and ABCA1 activity has been reported yet." (PMID 37312227, 2023). "Interestingly, Flaveny and colleagues reported upregulated levels of the LXR target gene ABCA1 in myeloid cells (macrophages and dendritic cells) infiltrating human TNBC samples, an observation in agreement with our results in human lung and melanoma samples." (PMID 36792589, 2023). "Of note, the enrichment of ABCA1 transcripts in monocytes/macrophages of non-responders turned out to be the most significant among all melanoma-infiltrating CD45+ cells (T lymphocytes, B lymphocytes, etc.; ABCA1 NR vs All = 1.40; P = 5.79 × 10-212; Wilcoxon rank sum test)." (PMID 36792589, 2023). "However, to date, ABCA1 implication in human melanoma progression has not been explored." (PMID 37312227, 2023).
hyperlipidemia (19 papers, 2013 to 2026). "The results of our research confirm the impact of the ABCA1 gene polymorphism rs2230806 on an increased risk of developing dementia among patients with hyperlipidemia." (PMID 41226793, 2025). "ABCA1 rs2230806 genotyping is a potential marker for the early identification of dementia risk in patients with hyperlipidemia, which supports the validity of exploring options for incorporating diagnostics based on molecular biology methods." (PMID 41226793, 2025). "In ApoE−/− mice, dandelion from alcohol extract of Taraxacum officinale enhanced macrophage cholesterol efflux via activating the PPARα/ABCA1 pathway, thereby ameliorating hyperlipidemia and associated inflammation." (PMID 40872505, 2025). "Loss or impaired function of ABCA1 or ABCG1 in human or experimental rodents leads to hyperlipidemia, excessive cholesterol accumulation in peripheral tissues, and an overwhelming inflammatory response." (PMID 23878415, 2013). "This mechanistic insight underscores the importance of considering both lipid-related genetic factors, such as ABCA1 polymorphisms, and systemic lipid status, such as hyperlipidemia, when assessing the risk and progression of neurodegenerative diseases and atherosclerotic complications." (PMID 41226793, 2025). "Allele C of rs12003906 is associated with decreased response to atorvastatin, pravastatin, or simvastatin in people with Hyperlipidemias as compared to allele G. Allele C, G, and G of rs2472507, rs2515629, and rs4149297, respectively are associated with increased expression of ABCA1 in HapMap cells." (PMID 38601677, 2024). "The aim of this study was to assess the usefulness of ABCA1, ABCB7, ABCB1, APOE, CYP46A1, and LRP1 genotyping as promising dementia risk factors among a wide group of patients diagnosed first with hyperlipidemia." (PMID 41226793, 2025). "We found a significant difference in ABCA1 (rs2230806) genotype distribution between the involved groups with hyperlipidemia and dementia vs. with hyperlipidemia." (PMID 41226793, 2025). "Reverse cholesterol transport (RCT), which is partly mediated by ATP-binding cassette transporter A1 (ABCA1), is a significant physiological link that delays hyperlipidemia progression." (PMID 37675019, 2022). "However, due to the relatively small sample size in this experiment, it is necessary to expand the study group in order to confirm the utility of ABCA1 rs2230806 genotyping as a predictive marker for the onset of dementia in individuals with hyperlipidemia." (PMID 41226793, 2025). "Another study indicated that quercetin might treat hyperlipidemia by promoting PPARγ and liver X receptor α (LXRα) expressions to upregulate ATP-binding cassette transporter A1 (ABCA1) genes and increasing cholesterol efflux from THP-1 macrophages in human acute monocytic leukemia cells." (PMID 34257817, 2021). "Siwei decoction attenuated high-fat diet-induced hyperlipidemia and reduced atherosclerotic plaque formation in New Zealand rabbits by potentiating the PPAR-LXRα-ABCA1 signaling axis." (PMID 40872505, 2025). "For example, sea buckthorn flavonoids improve hyperlipidemia by up-regulating PPARα/CPT-1α and PPARγ/ABCA1 signaling pathways." (PMID 38699583, 2024). "Notably, metabolic DEGs such as ACSL1, ABCA1, ABCG1, ACAT2, ALOX5AP, PLA1A, and PPARG were elevated in hyperlipidemia." (PMID 39853712, 2025). "In hyperlipidemia model, IOP‐A2 hypolipidemic role seems to occur mainly by promoting cholesterol metabolism and regulating the expression of the cholesterol metabolism‐related proteins CYP7A1, LXRα, SR‐B1, and ABCA1." (PMID 38628208, 2024). "Another research study found that EA stimulation of the “Fenglong” (ST 40) point contributed to increased expressions of ABCA1, PPARα, LXRα, and retinoid X receptor α messenger RNA, thus contributing to RCT, and somehow had a therapeutic effect on hyperlipidemia." (PMID 37675019, 2022).
Stroke (19 papers, 2018 to 2025). Sudden impairment of blood flow to a part of the brain due to occlusion or rupture of an artery to the brain. "Deficiency or genetic abnormalities in ABCA1 have increased the susceptibility to cerebrovascular diseases and can worsen outcomes following a stroke by impairing the blood-brain barrier and white matter." (PMID 39210350, 2024). "The combined effects of abnormal HDL-C levels (both low and high HDL-C levels) and rs2575876 AA genotype of ABCA1 gene on the risk of poor outcomes after stroke were investigated in this study." (PMID 39210350, 2024). "Due to the significant findings of HDL-C levels and ABCA1 gene rs2575876, the combined effects on the risk of worsening prognosis after stroke were further analyzed." (PMID 39210350, 2024). "The ABCA1 gene rs2575876 AA genotype combined with abnormal HDL-C levels exhibited a significantly heightened risk of post-stroke adverse outcomes at 1 and 3 months compared to patients with normal HDL-C levels and GG + GA genotype." (PMID 39210350, 2024). "We have previously demonstrated that deficiency of ABCA1 in the brain induces worse neurological functional deficits after stroke, increases BBB leakage and aggravates OL loss and WM injury." (PMID 35572941, 2022). "Recently, a proof-of-concept underlying the ABCA1/ApoE/HDL pathway mediates myelination during stroke repair ABCA1 knocked down in stroke mice showed a significant decreased in myelinated axons and myelin sheath thickness." (PMID 34436325, 2021). "Our data indicate that administration of ApoE2 minimizes the adverse effects of ABCA1 deficiency after stroke, at least partially by promoting cholesterol traffic/redistribution and GM/WM remodeling via increasing the ApoE/HDL/ApoER2 signaling pathway." (PMID 30373276, 2018). "More broadly, ABCA1 has been implicated in maintaining blood-brain barrier integrity, attenuating neuroinflammation, and supporting synaptic function across models of AD, PD, and stroke." (PMID 41602910, 2025). "ABCA1 expression is implicated in the neurorestoration post stroke." (PMID 40264650, 2025). "Furthermore, individuals with abnormal HDL-C levels and the rs2575876 AA genotype in the ABCA1 gene had a more significantly elevated risk of adverse outcomes at 1 and 3 months after stroke." (PMID 39210350, 2024). "Apart from pathogenic or likely pathogenic findings, 41 rare VUS in 325 stroke-related candidate genes were detected in 39 probands, including eight novel variants: ABCA1 p.H1223P, ACTA2 p.N298S, COL5A1 p.P930R, FBN1 p.Q514E, FBN1 p.K1052T, GP1BA p.P437*, RNF213 p.N1631Efs*34, and TSC1 p.P397del." (PMID 36580209, 2023). "However, the mechanisms underlying ABCA1-deficient induced deficits in WM remodeling after stroke are not fully understood." (PMID 32575457, 2020). "In this study, in order to investigate whether administration of cerebral ApoE2 would compensate for the loss of brain ABCA1 after stroke via increasing ApoER2, ABCA1fl/fl and ABCA1−B/−B mice, primary cultured neurons (PCNs), and oligodendrocyte progenitor cells (OPCs) were used." (PMID 30373276, 2018). "However, ApoE2 administration in ABCA1−B/−B stroke mice significantly increased brain ApoE and HDL levels and improved neurological function, which indicates that supplementation of ApoE2 reverses brain ABCA1 deficiency-induced neurological deficits after stroke." (PMID 30373276, 2018). "Previous studies have demonstrated a significant upregulation in Abca1 mRNA expression in the blood of stroke patients, and that Abca1 promotes efferocytosis and provides anti-inflammatory protection against cerebral ischemic injury." (PMID 39223647, 2024). "Administration of L-4F decreased T2DM-stroke induced vascular damage and BBB permeability even in brain-ABCA1-deficient mice." (PMID 35572941, 2022).
Stroke (continued). "ABCA1 overexpression in a mouse stroke model induced by GW3905, a liver-X receptor (LXR) agonist, increased blood HDL, both gray and white matter densities, oligodendrocyte progenitor cell number, and also improved functional outcomes after distal MCAO38." (PMID 34131232, 2021). "Brain evaluation in ABCA1-knockout mice has shown increased blood–brain barrier leakage, white matter/axonal damage, and functional deficits after stroke compared to ABCA1-expressing control mice." (PMID 34131232, 2021). "Database GSE16561 contained transcription expression profiles from 63 blood samples (39 stroke patients and 24 controls); mRNA expression of ABCA1 was significantly increased in stroke patients compared to controls." (PMID 34131232, 2021). "Increased mRNA expression of ABCA1 was found at all time points in the blood samples from stroke patients compared to controls, supporting the idea that ABCA1 expression is induced by brain ischemia." (PMID 34131232, 2021). "And intracerebral administration of ApoE and HDL in the knocked down ABCA1 stroke mice remarkably improved axonal myelination." (PMID 34436325, 2021). "Taken together, the present study suggests a therapeutic effect of the ABCA1/ApoE/HDL signaling pathway on WM remodeling in the ischemic brain after demyelination induced by stroke." (PMID 32575457, 2020). "Our previous study demonstrated that ABCA1-deficent mice exhibit decreased numbers of OLs and OPCs in the ischemic brain 7 days after stroke." (PMID 32575457, 2020). "Our previous study shows that GW3965, an agonist of syntheses of LXRs, increases myelin density and promotes WM remodeling after stroke in ABCA1fl/fl stroke mice via the upregulation of ABCA1 and by increasing the HDL level." (PMID 32575457, 2020). "Previous research demonstrated that specific deletion of brain-ABCA1 (ABCA1−B/−B) reduced brain grey matter (GM) and white matter (WM) density in the ischemic brain and decreased functional outcomes after stroke." (PMID 30373276, 2018). "Although ApoE2 increased brain ApoE/HDL levels and GM/WM density, negligible functional improvement was observed in ABCA1-floxed-stroke mice." (PMID 30373276, 2018). "In this study, we found that all three biomarkers, ABCA1, CLEC4E, and IRS2, were associated with the activation of NET formation and infiltration levels of neutrophils in the IS, implying their importance in stroke." (PMID 40264650, 2025). "For instance, specific deletion of brain-ABCA1 could reduce the density of white matter and gray matter in the ischemic brain and harm post stroke functional outcomes." (PMID 40264650, 2025). "Genetic variants in the ABCA1 gene may influence HDL-C expression, potentially exacerbating the risk of adverse outcomes following a stroke." (PMID 39210350, 2024). "We also test if L-4F treatment improves vascular and WM rewiring in T2DM stroke and whether L-4F decreases inflammation via ABCA1 dependent signaling pathway." (PMID 35572941, 2022). "Since L-4F can cross the BBB and reach the CNS, to further elucidate whether L-4F treatment-induced neurorestorative effect on T2DM-stroke is mediated by ABCA1 and ApoE signaling pathway, ABCA−B/−B mice were employed." (PMID 35572941, 2022). "The regulatory mechanisms for both miR-33-5p and miR-135b-5p on ABCA1 expression may provide potential therapeutic targets for treating stroke." (PMID 34131232, 2021). "ABCA1/ApoE were reported in many research about their effects in neural restoration after stroke." (PMID 33504361, 2021). "Brain ABCA1-deficient (ABCA1-B/-B) mice exhibit decreased WM remodeling as well as dysfunctional neurological outcome after stroke, and intracerebral supplementation of human ApoE or HDL reverses the deficits in ABCA1-B/-B stroke mice." (PMID 32575457, 2020).